SOX30 (SRY-box transcription factor 30)
Diseases named in the same sentence as SOX30 in open-access papers (continued):
Sharing a sentence is not in itself a finding about the gene and the disease.
prostate carcinoma (continued). "The expression and function of miRNAs can be critically dependent on the tissue and cell type involved, but our study suggests that miR-653-5p targets SOX30 and thus participates in prostate cancer progression." (PMID 31889959, 2019). "MiR-653-5p overexpression decreased SOX30 expression, while its inhibition increased SOX30 expression in prostate cancer cells." (PMID 31889959, 2019). "We found that SOX30 levels were significantly lower in prostate cancer cells than in normal prostate epithelial cells." (PMID 31889959, 2019). "Previous studies reported that SOX30 has a significant impact on Wnt/β-catenin signaling, which plays a crucial role in prostate cancer progression." (PMID 31889959, 2019). "Our data highlight the involvement of the miR-653-5p–SOX30–Wnt/β-catenin signaling axis in the progression of prostate cancer and provide novel insights into the molecular pathogenesis of prostate cancer." (PMID 31889959, 2019). "SOX30 overexpression in prostate cancer cell lines markedly reduced their proliferative ability and invasive potential." (PMID 31889959, 2019). "Our results suggest that inhibiting miR-653-5p restricts the proliferation and invasion of prostate cancer cells due to the inhibition of Wnt/β-catenin signaling through the miRNA’s targeting of SOX30." (PMID 31889959, 2019). "SOX30 knockdown significantly reversed the miR-653-5p inhibition-mediated inhibitory effect on the proliferation, invasion and Wnt/β-catenin signaling in prostate cancer cells." (PMID 31889959, 2019). "To date, little is known about the role of SOX30 in prostate cancer." (PMID 31889959, 2019). "Considering that Wnt/β-catenin signaling is highly activated and contributes to prostate cancer progression, targeting SOX30 to inhibit Wnt/β-catenin signaling may have a potential application in prostate cancer therapy." (PMID 31889959, 2019). "Targeting miR-653-5p to modulate SOX30 expression may represent a novel therapeutic strategy for prostate cancer." (PMID 31889959, 2019). "This study investigated the potential role of SOX30 in prostate cancer." (PMID 31889959, 2019). "Our study identified SOX30 as an miR-653-5p target gene in prostate cancer." (PMID 31889959, 2019). "We also examined the SOX30 expression pattern in a panel of prostate cancer cell lines." (PMID 31889959, 2019). "To validate whether SOX30 acts as a functional miR-653-5p target in regulating prostate cancer cell proliferation, invasion and Wnt/β-catenin signaling, we determined the effect of SOX30 silencing on the miR-652-3p inhibition-mediated anti-tumor effect." (PMID 31889959, 2019). "Moreover, our data show that knockdown of SOX30 partially reverses the miR-653-5p downregulation-induced tumor-suppressive effect in prostate cancer cells, indicating that SOX30 is a functional target of miR-653-5p in prostate cancer." (PMID 31889959, 2019). "Collectively, these results indicate that SOX30 is a miR-653-5p target gene in prostate cancer." (PMID 31889959, 2019). "SOX30 overexpression also significantly decreased the invasive potential of prostate cancer cells." (PMID 31889959, 2019). "Interestingly, SOX30 is commonly downregulated in prostate cancer compared with its level in normal tissues." (PMID 31889959, 2019). "Therefore, we evaluated the regulatory effect of SOX30 on Wnt/β-catenin signaling in prostate cancer cells." (PMID 31889959, 2019). "Moreover, transfection of the miR-653-5p mimics into prostate cancer cells significantly decreased SOX30 expression, while the miR-653-5p inhibitor markedly increased SOX30 expression." (PMID 31889959, 2019). "Nevertheless, our study suggests that the miR-653-5p–SOX30 axis may be involved in the progression of prostate cancer." (PMID 31889959, 2019). "This miR-653-5p/SOX30/Wnt/β-catenin axis may be involved in the progression of prostate cancer." (PMID 33152990, 2020). "However, whether SOX30 is involved in the development and progression of prostate cancer remains unknown." (PMID 31889959, 2019).
prostate carcinoma (continued). "MiR-653-5p and SOX30 may be novel and promising targets for prostate cancer." (PMID 31889959, 2019). "Therefore, SOX30 may serve as a potential anticancer target for prostate cancer treatment." (PMID 31889959, 2019). "However, whether SOX30 expression is regulated by miRNAs in prostate cancer remains unknown." (PMID 31889959, 2019).
acute myeloid leukemia (4 papers, 2018 to 2025). Acute myeloid leukemia (AML) is a group of neoplasms arising from precursor cells committed to the myeloid cell-line differentiation. "SOX30 has already been shown to be downregulated in acute myeloid leukemia (AML), which is highly associated with hypermethylation of the SOX30 promoter region." (PMID 33152990, 2020). "Herein, we revealed SOX30 methylation and its clinical implication in acute myeloid leukemia (AML) and myelodysplastic syndromes (MDS)." (PMID 30002740, 2018).
colon cancer (4 papers, 2017 to 2019). "Together, this study reveals that miR-645 can regulate oncogenesis in colon cancer with SOX30 being one of its targets." (PMID 28504690, 2017). "Moreover, SOX30 is an miR-645 target gene in hepatocellular carcinoma and colon cancer." (PMID 31889959, 2019). "The correlation between the levels of miR-645 and SOX30 was also substantiated through examining sampled colon cancer tissues with relatively low (No. 1–5) and high (No. 133–137) levels of miR-645." (PMID 28504690, 2017). "This suggests that although SOX30 inhibition contributes to miR-645-mediated CRC cell proliferation and survival, other unidentified targets of miR-645 may be more critical in executing the biological function of miR-645 in colon cancer." (PMID 28504690, 2017). "Moreover, overexpression of SOX30 only moderately inhibited promotion of CRC cell proliferation by miR-645, indicating that miR-645 may have more targets that contribute to its pro-proliferation effect in colon cancer." (PMID 28504690, 2017).
non-small cell lung carcinoma (3 papers, 2020 to 2025). A group of at least three distinct histological types of lung cancer, including non-small cell squamous cell carcinoma, adenocarcinoma, and large cell carcinoma. "To explore how SOX18 and SOX30 are epigenetically regulated in non-small-cell lung cancer (NSCLC), we analyzed the methylation status of three distinct CpG islets within their promoter regions across 30 patient samples (LSCC, n = 15; LUAD, n = 15)." (PMID 41373817, 2025). "Besides, SOX30 is regarded as a prognostic biomarker in terminal ovarian cancer patients; elevated SOX30 expression is regarded as a predictor of better survival among non-small cell lung cancer patients." (PMID 35836594, 2022). "Another interesting study also reports that SOX30 expression is particularly reduced in non-small cell lung cancer tissues compared to adjacent noncancerous tissues." (PMID 35836594, 2022). "The role of the SOX18 and SOX30 expression in non-small-cell lung cancers (NSCLCs) is not yet fully understood." (PMID 33152990, 2020).
ovarian carcinoma (3 papers, 2019 to 2023). A malignant neoplasm originating from the surface ovarian epithelium. "Another study also illustrates that increased SOX30 expression predicts more favorable OS in ovarian cancer patients." (PMID 35836594, 2022). "Another study indicated that the expression level of SOX30 might be used as a prognostic biomarker in patients with ovarian cancer." (PMID 38132438, 2023).
squamous cell carcinoma (3 papers, 2015 to 2025). A carcinoma arising from squamous epithelial cells. "In contrast, SOX30 expression was uniformly downregulated at both mRNA and protein levels, frequently linked to promoter hypermethylation, especially in squamous carcinoma." (PMID 41373817, 2025). "SOX30 expression is closely associated with histological types of NSCLC, and metastasis of adenocarcinoma (ADC) patients but not of squamous cell carcinoma (SCC) patients." (PMID 30514297, 2018).
breast carcinoma (2 papers, 2020 to 2022). "In terms of SOX30 expression in cancer, a previous study illustrated that SOX30 expression is reduced in breast cancer tissue compared to adjacent tissue." (PMID 35836594, 2022). "Similar to other types of cancer, in breast cancer higher SOX30 expression levels correlate with an enhanced disease-free survival (DFS) and an overall survival (OS)." (PMID 33152990, 2020). "Since it has been observed that SOX30 is negatively correlated with tumor size but positively correlated with DFS and OS, its further study might contribute to the outcome of breast cancer patients." (PMID 33152990, 2020).
chronic myeloid leukemia (2 papers, 2020). "In another study, SOX30 methylation has been correlated with disease progression in patients with chronic myeloid leukemia." (PMID 32700424, 2020). "Additionally, the methylation profile of the SOX30 promoter region has already been identified in chronic myeloid leukemia (CML) patients, but the biological role of this mechanism remains unrevealed." (PMID 33152990, 2020).
infertile (2 papers, 2021). "To determine the causes of infertile and testis impairment, we observed the gametes in epididymides and testes of Sox30−/− mice by histological examination." (PMID 33721419, 2021). "It is interesting that a transcriptome analysis of STA-PUT–fractionated cells from Sox30–/– infertile mice, revealed SOX30 as a testis-specific transcription factor essential for activating haploid differentiation programs during the later stages of meiotic prophase." (PMID 33748111, 2021). "However, the adult Sox30−/− male mice demonstrated complete infertility (fertile in 0/50)." (PMID 33721419, 2021).
malignant lymphomas (2 papers, 2019 to 2023). "For instance, up-regulation of miR-125b results in down-regulation of its target i.e., SRY-Box Transcription Factor 30 (SOX30) in malignant lymphomas that can be regarded as a useful biomarker, diagnostically and therapeutically." (PMID 36869286, 2023). "MiR-125b targets the SOX30 3′-UTR, and high miR-125b expression correlates with low SOX30 expression in the malignant lymphomas." (PMID 31889959, 2019).
autism (1 paper, 2023). Persistent deficits in social interaction and communication and interaction as well as a markedly restricted repertoire of activity and interest as well as repetitive patterns of behavior. "SOX30 I367V (HMG box location 31/33) was absent from gnomAD and found in two individuals within Geno2MP with autism, intellectual disability, and mild cerebellar vermis hypoplasia." (PMID 36672963, 2023).
colorectal cancer (1 paper, 2022). A primary or metastatic malignant neoplasm that affects the colon or rectum. "Sex-determining region Y-box containing gene 30 (SOX30) takes part in the progression of several cancers, while its clinical engagement in colorectal cancer (CRC) is obscure." (PMID 35836594, 2022).
leukemia (1 paper, 2018). A malignant (clonal) hematologic disorder, involving hematopoietic stem cells and characterized by the presence of primitive or atypical myeloid or lymphoid cells in the bone marrow and the blood. "In addition, a recent investigation reported SOX gene family expression in leukemia and found SOX30 expression was significantly downregulated in AML." (PMID 30002740, 2018).
tumor (20 papers, 2012 to 2025). "Intriguingly, recent studies revealed that decreased SOX30 expression is associated with miRNA dysregulation in tumor tissues." (PMID 31889959, 2019). "Sex-determining region Y-box containing gene 30 (SOX30) is a newly identified tumor-associated gene in several types of cancer." (PMID 31889959, 2019). "Through bioinformatics analysis, we found that SOX30 is a potential target gene of miR-653-5p, a tumor-associated miRNA." (PMID 31889959, 2019). "SOX30 expression was associated with clinical stage (p = 0.023), tumor size (p = 0.012) and long-distance metastasis (p = 0.022) in ADC patients." (PMID 30514297, 2018). "In our present study, we assessed an unknown clinical significance, specific tumor suppressor role and molecular mechanism of SOX30 in different subtype NSCLC using clinical association analysis, prognostic analysis and differentially expressed cell models." (PMID 30514297, 2018). "To define whether desmosomal genes are involved in the antitumor effects of SOX30, we focused on the most differentially expressed desmosomal genes associated with SOX30 and chose the three prominent tumor suppressors DSP, JUP and DSC3." (PMID 29855376, 2018). "Meanwhile, SOX30 exhibits a markedly different pattern: its expression is uniformly low across all regions, with the weakest signals found in tumor tissues." (PMID 41373817, 2025). "Our findings identify SOX7 and SOX30 as likely tumor suppressors, exhibiting reduced expression in NSCLC tissues, often through epigenetic silencing." (PMID 41373817, 2025). "In LSCC samples, SOX30 promoter regions tended to be highly methylated in tumor cores, with levels tapering off toward NMLT." (PMID 41373817, 2025). "This consistent downregulation, coupled with negative correlations to STAT3 and VCAM1 expression, especially in LSCC, supports the notion of SOX30 as a tumor suppressor." (PMID 41373817, 2025). "SOX30 can also inhibit tumor metastasis by upregulating e-cadherin and downregulating n-catherin, vimentin and fibronectin and preventing epithelial-mesenchymal transmission (EMT)." (PMID 38132438, 2023). "We observed statistically significant differences in the expression of SOX6, SOX8, SOX21 and SOX30 genes in healthy tissue vs. primary tumor samples." (PMID 38132438, 2023). "Multivariate Cox’s regression analysis illustrated that tumor SOX30 protein high expression was an independent factor for favorable OS (hazard ratio: 0.525, P = 0.034)." (PMID 35836594, 2022). "Further subgroup analysis discovered that a positive correlation was only found in tumor SOX30 protein expression with OS in patients with TNM stage II (P = 0.007)." (PMID 35836594, 2022). "Meanwhile, SOX30 mRNA expression (median (inter quartile range): 0.392 (0.221–0.744) vs. 1.000 (0.599–1.475)) was also reduced in tumor tissue compared to adjacent tissue (P < 0.001)." (PMID 35836594, 2022). "In our study, we found that tumor SOX30 protein and mRNA expressions were both reduced in CRC tumor tissue compared to adjacent tissue, which was partly consistent with previous studies." (PMID 35836594, 2022). "In order to explore the prognostic value of tumor SOX30 protein and mRNA expressions in CRC, we gathered the OS data of all CRC patients and we found that tumor SOX30 protein expression was positively correlated with accumulating OS (P = 0.017)." (PMID 35836594, 2022). "SOX30 IHC score (mean ± standard deviation: 2.6 ± 1.6 vs. 5.5 ± 2.6) was decreased in tumor tissue compared to adjacent tissue (P < 0.001)." (PMID 35836594, 2022). "SOX30 is shown to play a different role in tumor metastasis, and it regulates the Wnt/β-catenin-signaling pathway differently in AC and LSCC patients." (PMID 33152990, 2020).
tumor (continued). "SOX30 acts as a tumor suppressor and inhibits metastasis via an EMT process, which justifies the further study of its biological functions in OC." (PMID 33152990, 2020). "SOX30 can inhibit tumor-metastasis by directly binding to CTNNB1 promoter and result in a favorable prognosis." (PMID 31488089, 2019). "Although the tumor-suppressive function of SOX30 is well characterized, some key questions remain unanswered regarding the decreased SOX30 expression in tumor tissues." (PMID 31889959, 2019). "SOX30 displays tumor suppressive behavior, warranting future investigations into its therapeutic potential in the treatment of BC." (PMID 29880037, 2018). "In early-stage ADC patients, elevated SOX30 expression inhibits tumor-metastasis by directly binding to CTNNB1 promoter resulting in a favorable prognosis of these patients." (PMID 30514297, 2018). "In vitro proliferation, migration and invasion assays, and an in vivo nude mice model were utilized to assess the important role of desmosomal genes on SOX30-induced tumor suppression." (PMID 29855376, 2018). "The novelly specific role of SOX30 in ADC provides specifically effective therapies against tumor metastasis and useful information for prolonging ADC patient’s survival." (PMID 30514297, 2018). "In early-stage ADC patients, the elevated SOX30 represses Wnt/CTNNB1-signaling by directly binding to CTNNB1 promoter to inhibit tumor-metastasis and results in a favorable prognosis of these patients." (PMID 30514297, 2018). "From the data of our present study, the reason is that SOX30 plays different roles on tumor metastasis as differently direct regulation of CTNNB1." (PMID 30514297, 2018). "SOX30 was expressed to a lower degree in BC tissues in contrast to healthy bladder tissues adjacent to the tumor." (PMID 29880037, 2018). "SOX30 as a tumor metastasis suppressor is a favorable prognostic marker for the ADC patients at early stage, indicating that SOX30 has acted important role in the tumor onset of early stage, which further shows the powerful role of SOX30 in ADC." (PMID 30514297, 2018). "Knockdown of the expression of related desmosomal genes by miRNA significantly attenuated the inhibitory effect of SOX30 on cell proliferation, migration and invasion in vitro and on tumor growth and metastasis in vivo." (PMID 29855376, 2018). "Previously, we identified SOX30 as an epigenetically silenced tumor suppressor, inhibiting cell proliferation and inducing cell apoptosis in ADC but not in SCC." (PMID 29855376, 2018). "Our previous studies have showed that SOX30 functions as a tumor suppressor mainly through promoting tumor cell apoptosis with inhibiting proliferation in lung ADC13." (PMID 26330328, 2015). "This indicates that SOX30 methylation is influenced by tumor subtype, and its regulation may differ between squamous and adenocarcinoma histology." (PMID 41373817, 2025). "Correlation of tumor SOX30 with OS in subgroups categorized by TNM stage." (PMID 35836594, 2022). "Correlation of tumor SOX30 with clinicopathological features." (PMID 35836594, 2022). "In our study, negative associations were also found in tumor SOX30 with LYN metastasis, T stage, N stage, and TNM stage in CRC patients." (PMID 35836594, 2022). "In HCC tissues, the expression of SOX30 is decreased compared to adjacent non-tumor tissues." (PMID 35267473, 2022). "Moreover, SOX30 significantly inhibits tumor growth in nude mice, classifying SOX30 as a tumor suppressor in lung carcinogenesis." (PMID 33152990, 2020). "Moreover, SOX30 inhibits tumor cell proliferation and invasion, and promotes tumor cell apoptosis, suggesting a tumor-suppressive role." (PMID 31889959, 2019).